INS (insulin)
Diseases named in the same sentence as INS in open-access papers (continued):
Sharing a sentence is not in itself a finding about the gene and the disease.
Insulin resistance (continued). "Furthermore, PPARγ activation in mature adipocytes improves insulin sensitivity by inducing the expression of several genes involved in the insulin signaling cascade, and its downregulation is associated with insulin resistance." (PMID 38820505, 2024). "Insulin resistance is a clear risk factor for PE, and elevated insulin levels can lead to increased sympathetic nervous system activity and renal sodium retention, which may increase blood pressure." (PMID 38580943, 2024). "Cigarette smoking increases both the risk for insulin resistance and amyloid‐β (Aβ) aggregation, and impaired brain insulin/insulin‐like growth factor 1 (IGF1) signaling might increase risk factors for Alzheimer's disease (AD)." (PMID 38361318, 2024). "The released lactate could cause insulin resistance by suppressing glycolysis and impairing insulin signaling in SKM." (PMID 38255314, 2024). "Since inflammation and altered adipokine production triggered by HFD have been associated with insulin resistance and hepatosteatosis, we determined the development of hepatic steatosis and the alterations in insulin levels and insulin resistance in these mice." (PMID 39594650, 2024). "Chronic inflammation resulting from GD-induced increases in the levels of inflammatory factors, such as IFN-γ, IL-1β, and TNF-α in vivo, may contribute to insulin resistance and increase the risk of developing T2D by affecting insulin sensitivity." (PMID 39568808, 2024). "This is in line with emerging research that has linked AD with common T2DM phenomena, such as insulin resistance, dysfunctional insulin signaling, neuroinflammation, advanced glycosylation end products (AGEs), and metabolic dysfunction, earning it the name “type 3 diabetes”." (PMID 38255204, 2024). "GLP-1 agonists, including exenatide, liraglutide, lixisenatide, albiglutide, and taspoglutide can stimulate insulin secretion (similar to other insulin secretagogues), improve peripheral insulin resistance, decrease body weight, and reduce the risk of hypoglycemia for Type 2 diabetic patients." (PMID 39574978, 2024). "Maternal insulin resistance and subsequent hyperglycemia associated with obesity are major determinants of fetal macrosomia, leading to increased placental glucose transport and fetal insulin hypersecretion." (PMID 39331227, 2024). "Insulin resistance causing compensatory hyperinsulinemia can impair the insulin signaling pathway in vascular endothelial cells, leading to decreased nitric oxide (NO) production and vasodilatory dysfunction, which in turn causes vascular endothelial dysfunction." (PMID 38218859, 2024). "Furthermore, HT is known to induce an insulin-resistant state, which potentially contributes to the escalation of insulin resistance-associated disorders, including CVD." (PMID 39669655, 2024). "Interestingly, plasma S1P in humans was found to be associated with body fat, insulin levels, insulin resistance (by HOMA-IR), as well with cholesterol." (PMID 37794263, 2024). "Elevated CRP has not only been observed in patients with RA, but may also be associated with the development of induced insulin resistance and T2D by inhibiting insulin signaling." (PMID 39430749, 2024). "Some researchers believe that obesity may lead to insulin imbalance, and insulin resistance has been linked to depression." (PMID 38743203, 2024). "Dietary fiber, together with the consumption of low glycemic index foods, characteristic of the Mediterranean diet, can decrease insulin resistance, leading to a reduction in insulin levels, the increase in which is associated with a high risk of breast cancer." (PMID 38674877, 2024). "Next, we measured insulin sensitivity and glucose tolerance in Adgrl1VMH-deficient mice to further determine whether these mice show insulin resistance followed by impairments in glucose regulation." (PMID 37712955, 2024).
Insulin resistance (continued). "By contrast, the lipodystrophy and obesity clusters, which are characterized by reduced insulin sensitivity and higher insulin resistance, are most strongly associated with the AFA–EUR axis, in which effects are typically larger in EUR than in other ancestry groups." (PMID 38374256, 2024). "Aim of this study was to investigate the relationship between serum zonulin levels, both fasting and postprandial, with body mass index (BMI) and biochemical markers of insulin resistance (IR), insulin sensitivity, b-cell function and cardio-metabolic risk in obese non-diabetic youths." (PMID 38405153, 2024). "However, insulin sensitivity declines with the onset of the menopausal phase, and the risk of developing insulin resistance in menopausal women becomes similar to men, suggesting the critical role of female hormones in insulin sensitivity." (PMID 40988882, 2024). "Accordingly, it is conceptually possible that reduced hepatic insulin clearance could cause hyperinsulinemia-driven hepatic insulin resistance and fat accumulation in the liver (hepatic steatosis)." (PMID 39640841, 2024). "However, MetS, as a syndrome associated with insulin resistance, is thought to negatively affect insulin action in the peripheral tissues, including bone." (PMID 38731059, 2024). "Patients receiving corticosteroid therapy may require higher doses of insulin to counteract the insulin resistance caused by the steroids." (PMID 38510914, 2024). "However, both insulin resistance and hyperinsulinemia can contribute to cognitive impairment in adults, highlighting impaired tissue sensitivity to insulin as a pathogenic mechanism in AD." (PMID 38921025, 2024). "Increased insulin resistance on the other hand could cause higher levels of insulin and, as a result, increased androgen synthesis and decreased estrogen production." (PMID 39061008, 2024). "Also, the volumetric association with insulin and insulin resistance was observed only in FEP, which suggests a different mechanism in relation to psychotic illness." (PMID 39085221, 2024). "Though feline diabetes shares many features with spontaneous type 2 diabetes in humans, the underlying molecular mechanisms that predispose cats to decreased insulin secretion and insulin resistance remain unclear." (PMID 39684905, 2024). "Insulin resistance associated with increasing prevalence of obesity, is defined as the inability of insulin to activate insulin signalling to effectively regulate multiple cellular processes including the promotion of glucose uptake and utilisation as fuels in the heart." (PMID 38908792, 2024). "Moreover, increased fatty acid levels impede insulin-mediated glucose transport activity, hence causing insulin resistance." (PMID 39845797, 2024). "Clinical trials studying the effect of DPP-4 inhibitors on GDM have demonstrated a reduction in insulin resistance, alleviation of the symptoms associated with hyperglycemia, reduction in fasting plasma glucose and serum insulin, and downregulation of a biomarker indicative of glucose intolerance." (PMID 38339106, 2024). "The main contributors of this lipid class to the disease are ceramides, which are known to promote insulin resistance through inhibition of protein kinase B-mediated insulin signaling; ceramides have also been associated with toll-like receptor 4 dependent inflammation." (PMID 38999363, 2024). "Other effects include increasing insulin sensitivity by stimulating the expression of its receptors, reducing chronic inflammation by deactivating inflammatory cytokines associated with increased insulin resistance, and protecting against apoptosis." (PMID 39408723, 2024). "People susceptible to T2DM all have adverse factors such as aging and overnutrition, which can activate the innate immune system, induce macrophages and adipocytes in the body to secrete a variety of inflammatory factors, and further cause insulin resistance and insulin secretion dysfunction." (PMID 38725443, 2024).
Insulin resistance (continued). "Moreover, insulin resistance is associated with platelet hypersensitivity which can be explained by an impaired insulin signaling in platelets caused by endothelial dysfunction, hyperglycemia, and oxidative stress." (PMID 39175055, 2024). "In particular, VAT accumulation is associated with worsening of insulin resistance and derangements of insulin signaling, disturbance of lipid metabolism, modulation of the inflammatory and immune responses, pro-thrombotic state, and induction and activation of the angiotensin I–II system." (PMID 39331227, 2024). "Insulin resistance as a causative factor in this setting might represent one explanation based on the fact that circulating levels of insulin differ between T1DM and T2DM." (PMID 39037711, 2024). "Despite the evidence from clinical studies indicating a link between phospholipids and insulin sensitivity, it remains uncertain whether alterations in phospholipids are the cause or result of insulin resistance." (PMID 39195553, 2024). "Additionally, they identified increased BMI, reduced insulin sensitivity and insulin resistance as potential risk factors for ECDs to cause T1DM." (PMID 39337594, 2024). "Using a model of insulin resistance, studies have shown that a high-fat/high-sucrose diet is associated with impaired glucose-stimulated insulin secretion (GSIS) that might affect pancreatic β-cells." (PMID 38414818, 2024). "On the one hand, this is caused by monosaccharides and total carbohydrates intake reduction, which results in lower glucose and insulin spikes (and lower HbA1c levels) and, on the other hand, body weight loss itself (achievable easily on KD) reduces insulin resistance." (PMID 39200999, 2024). "GK rats show (i) an impaired glucose metabolism under the IPGTT underlying a state of insulin resistance, (ii) a consistently impaired insulin signaling activation in the brain, characterized by IRS1 hyper-activation but reduced downstream effects, and (iii) impaired cognitive functions." (PMID 38843768, 2024). "The aging process adversely affects β-cell function, exacerbating the deficiency in insulin production and heightening insulin resistance, potentially through mechanisms such as obesity, reduction in pancreatic parenchymal volume, and other contributing risk factors." (PMID 39911240, 2024). "Blood concentrations of bile acids are elevated in patients with non-alcoholic fatty liver disease (NAFLD) who exhibit insulin resistance, and inositol, with its insulin-mimetic properties, can play a role in diseases associated with insulin resistance and has the potential to modulate NAFLD." (PMID 38435365, 2024). "Interestingly, despite the common association between high BMI and increased insulin resistance, we observed that individuals with a BMI over 30 were receiving less insulin per kilogram of body weight compared to those with normal weight." (PMID 39218890, 2024). "Common risk factors causing IR in cats and humans include obesity, treatment with pharmacological agents that cause decreased insulin sensitivity, endocrinopathies associated with insulin resistance (i.e., hypersomatotropism), increasing age, and physical inactivity." (PMID 39684905, 2024). "For instance, the constant liberation of FFAs promotes the synthesis of very low-density lipoprotein, cholesterol, and gluconeogenesis in the liver, thus provoking impaired insulin signaling and glucose metabolism and, by this process, causing insulin resistance." (PMID 36900596, 2023). "In conclusion VFP or a VFPE prevented systemic inflammation, insulin resistance, and hepatic and renal damage in mice fed a high-fat diet associated with increased energy expenditure, improved mitochondrial function, and reduction in insulin secretion." (PMID 37175691, 2023).
Insulin resistance (continued). "Central fat is strongly linked to insulin resistance and type 2 diabetes, because visceral adipocytes induce defective insulin activity and convert cortisone to metabolically active cortisol, leading to impaired glucose tolerance, hyperinsulinemia, and insulin resistance." (PMID 37195871, 2023). "The main causes of type 2 diabetes are insulin resistance and a reduction in insulin." (PMID 38050514, 2023). "Insulin resistance increases the demand of pancreatic beta-cells to secrete insulin and, in susceptible individuals, the beta-cells eventually fail to produce and secrete sufficient amount of insulin to maintain normoglycemia." (PMID 36901964, 2023). "It has been found that weight loss/gain could increase/decrease insulin sensitivity, and obesity and insulin resistance are causally related." (PMID 37056675, 2023). "Moreover, copper can decrease PTEN protein levels in the adipocytes of mice, which behave as the negative regulator of insulin signaling; thus, copper deficiency can lead to insulin resistance." (PMID 37887373, 2023). "It has been suggested that vitamin K supplementation may lower the risk of T2DM due to its benefits for improving insulin sensitivity, glucose tolerance, and preventing insulin resistance." (PMID 37009872, 2023). "The significant pathophysiological features of type 2 diabetes are the decrease in insulin’s ability to regulate glucose metabolism (insulin resistance) and the decrease (or relative decrease) in insulin secretion caused by defects in pancreatic islet B cell function." (PMID 38093392, 2023). "Indeed, rare deactivating mutations in Akt or upstream proteins cause insulin resistance and reduced activation of Akt or its upstream proteins has been observed in insulin-resistant muscle and adipose tissues of mice, rats and humans." (PMID 37248992, 2023). "In clinical practice, an atypical response to GDM treatment, e.g. no/little response to diet or metformin treatment, but strong response to insulin treatment indicates low insulin resistance, and is suggestive of insulin deficiency, thus justifying autoantibody testing." (PMID 38192417, 2023). "Therefore, resveratrol, with underlying mechanisms, including improving the insulin signaling pathway, mitochondrial function, reducing inflammation, and oxidative stress, can improve insulin resistance in the skeletal muscle of type 1 diabetic rodents." (PMID 38027557, 2023). "Therefore, reduction of food intake (anorexic effect of surgery), reduction of insulin resistance (long-term weight reduction after surgery) and increase of insulin secretion (which is weight loss independent) improves diabetes." (PMID 36826628, 2023). "Insulin resistance usually occurs due to increased visceral obesity in excess, and the relationship between insulin resistance and impaired cognitive function may be linked to insulin-degrading enzymes (IDE)." (PMID 38027119, 2023). "APMAP caused insulin resistance through IRS-1/insulin sensitive genes/free fatty acids pathway." (PMID 36766716, 2023). "The study found that the treatment of Dai Zong Fang combined with acupoint catgut embedding can significantly improve clinical symptoms, reduce body weight, increase insulin sensitivity, and improve insulin resistance in obese patients with spleen deficiency and dampness retention." (PMID 38050318, 2023). "Moreover, oxidative stress has been implicated in the pathogenesis of insulin resistance through disruption of insulin signaling and dysregulation of adipocytokines." (PMID 38133386, 2023). "It is possible that this may be due to the association between insulin and weight gain, aggravating the insulin resistance, promoting oxidative stress, and shortening the telomere length." (PMID 36979709, 2023). "Finally, it is known that physical activity reduces insulin levels and risk of insulin resistance independently of weight status." (PMID 37420130, 2023).
Insulin resistance (continued). "The increase in insulin resistance noted in our male mice may go in line with the notion that elevated insulin levels causes activation of adipose tissue inflammation and apoptosis." (PMID 37198225, 2023). "Ceramides may be associated with insulin resistance because they may interfere with insulin signaling." (PMID 37009872, 2023). "In line with the sex-specific effects of paternal iAs exposure on glucose metabolism, in utero iAs exposure causes insulin resistance and mild glucose intolerance in female offspring but higher insulin sensitivity and unchanged glucose tolerance in male offspring in a rat model." (PMID 37691128, 2023). "In addition, neutralization of TNFα significantly increased insulin-stimulated peripheral uptake of glucose, a result that demonstrates a strong association between higher TNFα levels and insulin resistance." (PMID 37935669, 2023). "Gestational diabetes mellitus (GDM) refers to insulin resistance that is caused by hormonal or metabolic changes during pregnancy (for example, the increase of blood sugar caused by the insufficient compensatory secretion of insulin." (PMID 36983587, 2023). "Furthermore, female C57BL6J mice are known to be more insulin-sensitive, and therefore less susceptible to the development of insulin resistance, than male C57BL6J mice, which in turn improves the rates of fatty acid oxidation." (PMID 38140297, 2023). "Remarkably, mitochondrial overload might generate intermediate molecules interfering with the insulin signaling and causing insulin resistance." (PMID 37152929, 2023). "The occurrence of insulin resistance in T2DM patients may also be caused by an abnormal synthesis of insulin, a mutation of insulin receptors, or the presence of an insulin antagonist." (PMID 38044940, 2023). "Studies have shown that PM2.5 may cause insulin resistance in adipose tissue, liver, blood vessels, and other tissues and organs by inhibiting insulin signal transduction." (PMID 37999546, 2023). "The two leading causes of type 2 diabetes are insufficient insulin secretion and insulin resistance that may be mediated by adipose tissue." (PMID 37050926, 2023). "The primary secretory molecules and important signaling pathways connected to insulin signaling are significantly altered in obese people, which leads to the development of insulin resistance, which is primarily caused by increased inflammatory processes in adipocytes." (PMID 36826001, 2023). "Deficiency of insulin signaling permits unregulated adipose tissue lipolysis, leading to dyslipidemia and the ectopic deposition of lipids in non-adipose tissues such as the liver, further causing hepatic steatosis and exacerbating systemic insulin resistance." (PMID 37834368, 2023). "DAG is linked to altered insulin signaling and insulin resistance through the activation of hepatic protein kinase C, which results in reduced insulin-stimulated phosphorylation of IRS-2 and Akt2 and, thereby, the ability to activate glycogen synthesis and decrease gluconeogenesis." (PMID 37371902, 2023). "However, its dysregulation can interfere with insulin functions and cause hepatic insulin resistance (IR)." (PMID 38132860, 2023). "The Insulin Resistance Intervention after Stroke (IRIS) trial showed that pioglitazone which improves insulin sensitivity could decrease the risk of AIS or myocardial infarction in nondiabetic patients with a recent transient ischemic attack (TIA) or AIS." (PMID 37633905, 2023). "A post hoc analysis of the POUNDS LOST RCT showed that in response to high-fat diets, participants with the highest genetic risk score showed increased fasting glucose, insulin resistance, and decreased insulin sensitivity at 6-month follow-up than those with low-fat diets." (PMID 37610590, 2023).